CD4 (CD4 molecule)
Diseases named in the same sentence as CD4 in open-access papers (continued):
Sharing a sentence is not in itself a finding about the gene and the disease.
tumor (continued). "Importantly, TLSs in HPV-positive tumors were located closer to the tumor area and enriched in activated immune cells, including ICOS+ CD4 T- cells, memory T- cells, and CD21+ B- cells." (PMID 41254766, 2025). "CD4+ and CD8+ T cells cultured in CM obtained from mGSCs pre-treated with ITD-1 or from TGFBR2-knockdown GBM cells displayed enhanced TCR-independent tumor cell-killing capacity compared to T cells cultured in either unconditioned medium or in CM from control mGSCs (DMSO-treated or no doxycycline)." (PMID 40277917, 2025). "To confirm our findings from the scRNA‐seq resource, we next performed immunofluorescence staining of B16‐F10 mouse tumor specimens and we observed that Fulvestrant combined with anti‐PDL1 increased the infiltration of CD8+, CD4+, and GZMB cells into the tumors compared to the control group." (PMID 40974370, 2025). "In the investigated tumor areas, combination of PD-1 immune checkpoint blockade with Ad5/11-αCD3TAT-Trimer showed a significantly higher amount of total T cells including both total CD8+ and CD4+ T cells (Fig. EV5H)." (PMID 39789356, 2025). "Furthermore, the proportion of CD4+CD25+FoxP3+ Tregs in tumors decreased by approximately 10% in the poly IC + IF4G3986–994 group, indicating a reduction in the immunosuppressive tumor microenvironment alongside robust immune activation." (PMID 40283929, 2025). "In most epithelial cancers, elevated p62 expression corresponds to increased tumor purity, reduced CD8+/CD4+ T-cell and dendritic-cell infiltration, and enhanced expression of immunosuppressive checkpoints such as PD-L1 and B7-H3, supporting a role in immune exclusion." (PMID 41291343, 2025). "Combined DAC/IL-33, but not the single treatments, induced significant increase in tumor-infiltrating CD4 and CD8 T cells with respect to untreated mice." (PMID 40317004, 2025). "In PanC, the tumor microenvironment is predominantly infiltrated by CD4+ T cells (Th2) rather than CD8+ T cells." (PMID 40136652, 2025). "Nevertheless, studies have proposed that B7-H3 may interact with a receptor expressed on activated CD4+ T cells and CD8+ T cells, which could be recognized by B7-H3 expressed on APCs or tumor cells." (PMID 41463642, 2025). "Immunofluorescence (IF) staining of CT2A tumor tissues revealed that, compared with vehicle treatment, cinobufagin treatment significantly increased the infiltration of CD45+ immune cells, with a particularly notable increase in CD4+ T cells and CD8+ T cells." (PMID 39901195, 2025). "A well-defined ratio of CD4 + and CD8 + T cells, such as a 1:1 ratio, has been shown to enhance efficacy by combining the direct tumour-killing ability of CD8 + T cells with the cytokine support provided by CD4 + T cells, particularly Th1-skewed cells that secrete IFN-γ, IL-2, and TNF-α." (PMID 40624498, 2025). "In the treated right-sided tumors, XPDT therapy significantly increased T cell infiltration in the tumor, as indicated by the significant increase in CD3+ T cells (inclusive of CD4+ and CD8+ T cells) in the RT + pYSM–treated tumors when compared to the control group." (PMID 40138411, 2025). "The TIME in OC predominantly consists of immunosuppressive cells, such as regulatory T cells (Tregs) and M2 macrophages.The infiltration of CD8+ T cells and activated CD4+ T cells, which are integral to anti-tumor immunity, is notably limited in OC." (PMID 40564014, 2025). "Another approach to reactivate the immune system employs pro-inflammatory cytokines such as interleukin-12 (IL-12), which activates NK cells, effector CD4 T cells and cytotoxic CD8 T cells and induces IFNγ expression for direct tumor cell targeting and antiangiogenic effects." (PMID 40342421, 2025). "Compared to the control group, the sole depletion of either CD4+ T or CD8+ T cells did not modify tumor growth dynamics." (PMID 40135850, 2025).
tumor (continued). "Based on this lack of killing capacity, the TCR of clone 1.5.F1DNMT3A is not expected to produce T cells with direct anti-tumor potential upon transfer to CD4 T cells." (PMID 40151616, 2025). "In the absence of CD14+ TAMs, human CD4+ T cells responded to tumor antigen with TNF production (first column)." (PMID 40872773, 2025). "In tumor-bearing mice, pulmonary ILC2s, as well as tumor-infiltrating ILC2s adoptively transferred at a ratio of 1:60 relative to tumor cells, significantly enhance the infiltration of CD4+ and CD8+ T cells and eosinophils into the tumor microenvironment, thereby suppressing tumor growth." (PMID 41200171, 2025). "Intriguingly, DSF treatment impaired LCK activation in both tumor-infiltrating CD4+ and CD8+ T cells (data not shown)." (PMID 40759573, 2025). "Further, IL-10, a suppressive cytokine that dampens CD4+ T-cell expansion and function, was significantly lower in DCV2-treated groups, suggesting that DCV2 more effectively counters immunosuppression within the tumor microenvironment." (PMID 40573908, 2025). "Bioinformatic analyses revealed that LINC00892 expression is positively correlated with immune cell infiltration, including CD4+ and CD8+ T cells, and negatively correlated with tumor-promoting Th2 cells, suggesting its role in shaping the tumor immune microenvironment." (PMID 40308809, 2025). "Although such studies have been instrumental in revealing the various effector and regulatory roles of CD4+ T cells in tumor immunity, none have allowed insights into the natural ontogeny of tumor-specific CD4+ T cells in unmanipulated conditions." (PMID 40196575, 2025). "Our results support the requirement of CD4+ T cells for tumor control in an MHCII-dependent manner, and for sustained control of GBM, which depends on a memory CD4+ T-cell subset, whose signature is also correlated with better survival in our G207 clinal trial patients and TCGA-GBM patients." (PMID 39885128, 2025). "The cellular interaction network diagram demonstrated the number and weight of interactions between various types of cells, with the strongest interactions between tumor cells and several major immune cells, including myeloid cells, CD8+ T cells, CD4+ T cells, NK cells, and B cells." (PMID 40018995, 2025). "Moreover, a tendency for higher CD4+ T cells and CD8+ T cells in tumours harbouring ERBB2 amplification was detected." (PMID 40650126, 2025). "Although tumors can exclude immune cells from entering, once inside, tumors create a hostile environment for immune cells, where antitumor effector cells, CD4+ TH1 cells, CD8+ T cells, and NK cells are at a competitive disadvantage, given the augmented metabolic activity of tumor cells." (PMID 41373645, 2025). "In the majority of our previous experiments, the MATE trimer seemed to show a more favorable profile regarding the quality of T-cell activation such as the CD8/CD4 T cell ratio, triggering of tumor-specific T cells and a higher number of PD1-positive cells within the tumor." (PMID 39789356, 2025). "However, this expansion seemed to be broader in the tumor microenvironment and was not limited to CD8+ T cells only but included CD4+ T cells, possibly through antigen spreading, despite the lack of an MHC-II-restricted antigen in our vaccine design." (PMID 40333215, 2025). "A recent study of intratumoral immune signaling highlights immune triads as critical to tumor cell elimination; these triads are composed of CD4+ and CD8+ T cells engaging with the same dendritic cell, with the spatial positioning of these cells serving as a key predictor of anti-tumor activity." (PMID 41295524, 2025). "Since CD4+ and CD8+ T cells provide tumor cell immunity, reduced lymphocyte numbers usually indicate the suppression of tumor immunity, providing favorable conditions for tumor progression." (PMID 40277779, 2025).
tumor (continued). "Furthermore, intra‐tumoural TLS tissues exhibited higher levels of CD4+Bcl6+ Tfh cells and CD4+Foxp3+ Tregs compared with adjacent tissues, indicating a robust and effective antitumour immune response (immune active)." (PMID 39924620, 2025). "Thus, changes in both CD4+ and CD8+ T cells were provocative for spleens with IGRT, emphasizing the importance of this modality in preparing the tumor for a productive antitumor response." (PMID 40813233, 2025). "CD4+ helper T cells augment this response by producing interleukin-2, tumor necrosis factor-α, and interferon-γ, which promote CTL function, enhance macrophage and NK cell activity, and increase tumor antigen presentation." (PMID 41194932, 2025). "Notably, the YQHXJDD ELNVs group displayed the highest CD4/CD8 ratio, suggesting that YQHXJDD ELNVs can alleviate the immunosuppressive tumor microenvironment and enhance T cell-mediated immune activity." (PMID 41170390, 2025). "In a Phase I/II trial, intramuscular administration of mRNA-4650 in CRC patients successfully induced CD8+ and CD4+ T cell responses against neoantigens, without significant adverse effects or tumor relapse." (PMID 40733666, 2025). "Tumor cells can be recognized and directly killed by activated CD8+ or CD4+ T cells after the tumor antigens are processed and presented by antigen-presenting cells (APCs) through major histocompatibility complex class I (MHC class I) or class II (MHC class II) molecules." (PMID 41050655, 2025). "Furthermore, antigen-presenting cells (APCs), such as dendritic cells and macrophages, present tumor antigens to CD8+ and CD4+ T cells through MHC I and MHC II molecules, initiating and sustaining the antitumor immune response." (PMID 40936903, 2025). "Tumor‐derived IL‐2 and TGF‐β convert CD4+CD25− cells into Tregs." (PMID 41143064, 2025). "Histological and flow cytometric analyses conducted after patient treatment, confirmed the presence of activated CD8+ T cells and enhanced immune responses in tumour tissues, demonstrated by increased circulating CD8+ and CD4+ central memory T cells and CD8+ memory precursor effector cells (MPECs)." (PMID 40619749, 2025). "After adjusting for tumor purity, the analysis revealed that immune-active cells, specifically B cells and CD4 + T cells, exhibited a negative correlation with TOPK expression." (PMID 40826334, 2025). "We observed a decrease of Treg cells (CD45+CD4+FoxP3+) in tumor-draining lymph nodes (tdLN) in NPc-Rel-treated mice compared to PBS-treated mice; however, the percentages of the tdLN T helper cells (CD45+CD4+) and cytotoxic T cells (CD45+CD8+) were similar among all groups." (PMID 40134427, 2025). "Questions remain regarding whether both CD8+ and CD4+ epitopes are necessary and whether vaccine-induced CD4+ T-cell responses can promote CD8 + T-cell priming and differentiation for improved tumor control." (PMID 40629076, 2025). "Of note, Foxp3+ Tregs did not efficiently infiltrate into the lung compared with effector CD4+ T cells, while tumor-infiltrating Treg cells highly expressed ICOS regardless of host age or anti–PD-L1 therapy." (PMID 40198121, 2025). "Patients with NSCLC who experienced a later relapse (after >2 years) revealed an increased CD4+ T cell density in both the tumor core (nonsignificant) and the tumor margin compared to patients with early relapse (<1 year)." (PMID 40561008, 2025). "HQF further enhanced CD4+ and CD8+ T cell infiltration within the tumor microenvironment." (PMID 39972480, 2025). "In addition, this team also provided detailed protocols for manufacturing CD4-and/or CD8-targeted LV and discussed how the protocol can be easily adapted to produce LV targeting other tumor antigens in vivo." (PMID 40821123, 2025). "T cell depletion assay showed that blocking CD8 attenuated the tumor suppression effect brought by Hmgb2flox/flox;Cd4-Cre mice, while tumor growth was not affected by CD4 antibody." (PMID 40315321, 2025).
tumor (continued). "Precisely, the lymphoid cells can promote or suppress tumor growth by modulating immune responses through B-cells, CD8+ cytotoxic T cells, CD4+ helper T-cells and regulatory T cells, while the natural killer (NK) cells employ cytotoxic activity to target cancer cells." (PMID 40438111, 2025). "This combination significantly increased CD4+ and CD8+ T cell infiltration within tumor tissue, markedly enhanced the cytotoxic activity of tumor-specific cytotoxic T lymphocytes (CTLs), and reversed both IL-2 depletion and elevated PD-L1 expression induced by sorafenib intervention." (PMID 40926993, 2025). "Within the tumor immune infiltrate, CXCR4 is mainly expressed by both CD4+ and CD8+ lymphocytes." (PMID 40362664, 2025). "HSV-1 OV-mOX40L activated CD4 and CD8 T cells, as evidenced by increased IFNγ and granzyme b production, and increased migration of immune cells into the TME, similar to our observations with the UN-KC-6141 tumor model." (PMID 40430543, 2025). "Additionally, the treatment induced a significant proliferation of CD4+ and CD8+ CAR-T cells, suggesting the development of memory T cells capable of providing long-term protection against tumor recurrence." (PMID 40382583, 2025). "Thus, MDRVV was shown to induce immunogenic cell death and increase CD4+ and CD8+ T-cell infiltration in the tumor microenvironment, suggesting that it promotes the cancer-immunity cycle." (PMID 40867310, 2025). "Furthermore, when analyzing tumor microenvironments, it was found that there is a significantly elevated number of CD4 and CD8 T-cells within tumors during the morning; it is said that the immune system has a higher anti-tumor ratio within the morning hours." (PMID 40416194, 2025). "However, laboratory experiments have shown promising responses from CD4+ and CD8+ T cells against tumor antigens." (PMID 40625850, 2025). "Specifically, a significantly higher ratio of CD4+ T cells, relative to the total tumor cells (but not CD45+ cells), was detected in DB-treated tumors." (PMID 40867314, 2025). "Exhausted or dysfunctional CD8+ and CD4+ TILs exhibit the B cell-recruiting C–X–C pattern chemokine ligand 13 (CXCL13), which often indicates that B cells are designed to provide assistance in the face of tumor persistence." (PMID 40297580, 2025). "Indeed, PD-1high CD4+ T cells isolated from MMRd ECs co-expressed other activation markers such as CD38, HLA-DR, ICOS, BCL6, CXCL13 and KI67, were proven to be tumor-reactive T cells and correlated with improved prognosis in ECs with high TMB." (PMID 39544936, 2024). "Unlike FoxP3+ CD4+ T cells, which typically exhibit regulatory functions that can suppress anti-tumor immune responses, FoxP3- CD4+ T cells can enhance anti-tumor activity." (PMID 39335203, 2024). "Examination of the TME of the 5-FU + E.coli group showed no enhancement of CD4+ or CD8+ tumor-infiltrating lymphocytes (TILs), indicating that the treatment combination was ineffective in elevating anticancer adaptive immunity." (PMID 38225455, 2024). "Some groups have engineered VSV to express human papillomavirus oncogene E7 or human oncofetal antigen 5T4, which generate CD4+ and CD8+ T cell-specific responses that traffic to the tumor site when administered intratumorally in mice with melanoma and colorectal cancer xenografts." (PMID 39861805, 2024). "Other OVs, like engineered HSV-1 and influenza A viruses, have shown enhanced antitumor responses when combined with ipilimumab, primarily by increasing immune cell infiltration (CD4+, CD8+ T cells) and reducing immunosuppressive Tregs in the tumor microenvironment." (PMID 39684701, 2024). "The authors also reported a significant association between increased stromal IL6 and reduced influx of anti-tumour CD3+ and CD4+ T cells, and mass cytometry analysis indicted an increased presence of immunosuppressive populations in the TME of the high IL6 subgroup." (PMID 39766336, 2024).
tumor (continued). "Depletion of CD4+ T cells, but not CD8+ T cells, prevented anti-CTLA-4 Ab-mediated anti-tumor effects, suggesting dependence on CD4+ T cells." (PMID 39106430, 2024). "The In vivo mouse experiments demonstrated that IL-33 could induce the recruitment of eosinophils, CD4+ T cells, CD8+ T cells, and macrophages to HCC, significantly reducing the number of tumor nodules." (PMID 39308686, 2024). "Our data further clearly show that targeting B7-H3 with our bsAb CC-3 induces potent and target-restricted activation of CD4+ and CD8+ T cells that results in pronounced tumor cell killing, but also T cell proliferation that is particularly important to combat high tumor burden." (PMID 38765008, 2024). "By using a multiplexed IF using a panel, we were able to distinguish broad immune populations cells (B cells, CD4+, CD8+, macrophages, and Tregs), which allowed an unparalleled simultaneous analysis of populations and relative proximity within a human tumor ex vivo." (PMID 38968363, 2024). "Unlike their CD8+ counterparts, CD4+ memory T cells are persistently present, which is vital for a sustained response to tumor antigens." (PMID 39877377, 2024). "In addition, with the assistance of CD4+ T cells (CD40-CD40L interaction), CD8+ CTLs further exert their effects on tumor cell killing." (PMID 38515134, 2024). "Among the 39 TCGA tumor types and subtypes, the expression of PCSK9 in BRCA, BRCA-Luminal, and THCA was significantly positively correlated with the infiltration of B cells, CD8+ T cells, CD4+ T cells, macrophages, neutrophils, and DCs." (PMID 38600469, 2024). "Our prior studies revealed the crucial role of CD4+ Th1 cells in orchestrating systemic and durable antitumor immunity, which contributes to the satisfactory outcomes of the novel cryo-thermal therapy in the B16F10 tumor model." (PMID 38827732, 2024). "In tumor-specific immune responses, cDC1s are key players, presenting tumor antigens to CD8+ T cells through MHC-I cross-presentation and driving Th1 differentiation among CD4+ T cells." (PMID 39308861, 2024). "Furthermore, the tumor cells were more incohesively arranged than those seen in the pretreatment biopsy, accompanied by an obviously greater degree of CD3-, CD4-, or CD8-positive mononuclear cell infiltration inside the tumor nests after immunotherapy." (PMID 39517020, 2024). "Similarly, nanovaccines comprising epitope peptides from CD4+ and CD8+ T cells have effectively stimulated anti-tumor immune responses in GC patients." (PMID 39397869, 2024). "We observed a considerably higher proportion of T cells – including both CTL and CD4+ cells – in the tumor areas compared to the TLS areas, the T cell population representing approximately 80% of the phenotyped cells within the tumor tissue and 40% in the TLS areas." (PMID 39376565, 2024). "In tumor models of melanoma and fibrosarcoma, myeloid-specific SHP-2 ablation led to increased tumor infiltration by proinflammatory monocytes and concomitant recruitment and activation of CD4+ and CD8+ TEF cells." (PMID 39516356, 2024). "MDSCs can polarize macrophages toward the M2 phenotype, which promotes tumor progression, secrete IL-10 and TGF-β, induce the proliferation of Treg cells, and indirectly inhibit CD4+ Th1 and CD8+ T cell activity through the inhibition of DCs, exerting immunosuppressive functions." (PMID 38404689, 2024). "We also found that CD4+CD25+ cells are able to preferentially adhere to TECs regardless of their tissue of origin (tumor, normal kidney tissue, or peripheral blood)." (PMID 39516665, 2024). "Intricate composition of immune cells and stromal cells in OPSCC has been unveiled, including distinct signatures of helper CD4+ T cells and B cells in HPV+ tumor, fibroblasts with specific prognostic value, and comprehensive cellular communications in the TME." (PMID 39105803, 2024). "Decreased IFN-γ+ CD4+ and IFN-γ+ CD8+ T cells in tumor tissue." (PMID 39906741, 2024).